AQP3 (aquaporin 3 (Gill blood group))
Diseases named in the same sentence as AQP3 in open-access papers (continued):
Sharing a sentence is not in itself a finding about the gene and the disease.
tumor (continued). "AQP3 could support tumor metabolism by enabling glycerol uptake, a key substrate of the cellular production of ATP, the essential energy source for cellular biosynthesis and, consequently, cell division and proliferation." (PMID 32075009, 2020). "Elevating the expression of AQP3 promoted tumor proliferation and migration." (PMID 32500032, 2020). "Furthermore, AQP3 was highly expressed in 70% tumor samples (84/120) and low or negatively expressed in the remaining 36 cases (30%)." (PMID 31197130, 2019). "A second study using PDAC from a relative larger cohort of Chinese patients displayed higher AQP1 and AQP3 expression as compared to benign pancreatic tissue, and the expression level was inversely correlated with the tumor, node metastasis stage of the disease." (PMID 31614661, 2019). "In addition, AQP3 expression was inversely correlated with the tumor differentiation status and aggressiveness." (PMID 31614661, 2019). "Besides, co-expression of AQP3 and AQP5 in HCCs has a significant association with serum AFP and tumor stage and grade." (PMID 25886458, 2015). "Larger expression of AQP3 may confer to the cell a more tumor like phenotype and contributes to explain the presence of this protein in many different tumors." (PMID 26367709, 2015). "The results suggest that AQP3 may mediate estrogen-promoted tumor development in ER-positive breast cancer." (PMID 26219409, 2015). "Correspondingly, the resistance of AQP3 null-mice toward skin tumors might arise through reduced tumor cell glycerol metabolism and ATP generation." (PMID 24653705, 2014). "Overexpression of AQP3 was observed on tumor cells in oral squamous carcinoma." (PMID 24918928, 2014). "In addition, combined AQP3 and AQP5 protein expression was significantly associated with serum AFP (P = 0.008), tumor stage (P = 0.006), and tumor grade (P = 0.006)." (PMID 24224160, 2013). "Moreover, combined AQP3 and AQP5 protein expression was significantly associated with serum AFP (P = 0.008), tumor stage (P = 0.006), and tumor grade (P = 0.006)." (PMID 24224160, 2013). "Interestingly, 60% of pT1 tumours were found to be AQP3 positive while the remaining specimens revealed complete absence of AQP3." (PMID 23043286, 2012). "The retrospective design of the study and the distinction between AQP3-positive versus AQP3-negative tumours may be oversimplistic." (PMID 23043286, 2012). "Loss of AQP3 protein expression was defined as complete absence of the protein within the whole tumour." (PMID 23043286, 2012). "Lack of AQP3 protein expression in pT1 tumours was shown to be associated with progression towards muscle-invasive disease." (PMID 23043286, 2012). "The present study suggested downregulation of AQP3 may suppress tumor-specific vascularization." (PMID 39611488, 2025). "In the same study, AQP3 and AQP5 were associated with increased levels of EGFR, proliferation marker Ki-67, cytokeratin 7 and vimentin, while E-cadherin was found to be decreased, indicating the contribution of these AQP isoforms to EMT, tumor growth and invasion." (PMID 39941100, 2025). "Therefore, it is hypothesized that elevated expression of AQP1 and AQP3 may facilitate tumor cell formation." (PMID 39440058, 2024). "Importantly, AQP3 knockdown prevented the LPS-induced increase in tumor growth." (PMID 38463942, 2024). "In vivo xenograft model further demonstrated that AQP3 could promote tumor growth induced by LPS." (PMID 38463942, 2024). "However, the underlying functions and mechanisms of AQP3 in the tumor microenvironment (TME) of LUAD have not been elucidated." (PMID 39060229, 2024). "Moreover, the number of surface lung nodules was significantly higher in the WT + GW1929 + urethane group, demonstrating that Aqp3 deletion might decrease tumor growth while PPAR-γ agonists can promote tumor progression." (PMID 39060229, 2024).
tumor (continued). "Moreover, In colorectal cancer, both AQP3 and epidermal growth factor receptors have a function in tumour progression and metastasis; consequently, both may be suitable candidates for suppression." (PMID 38336645, 2024). "Furthermore, because of its specificity to UEC, AQP3 expression may indicate primary UEC if the tumor is histologically diagnosed as EC." (PMID 37713813, 2023). "So far, there is a clear consensus in the literature that AQP3 is involved in the development of lipid structures by providing glycerol and that AQP3 is involved in cell proliferation and growth by encouraging ATP and therefore may play a key role in tumor energy metabolism." (PMID 36233821, 2022). "In addition, the tumor-related functions of AQP3 in tumors have also been reported." (PMID 35957833, 2022). "Similarly, AQP3 had a lower expression in FOXO1-transfected SUM159PT (SUM159PT-FOXO1+) xenografts than in the control SUM159PT cells, and such an opposite relationship was also observed in in vivo mouse tumor samples after CAP treatment but with elevated AQP3 intensity." (PMID 35637961, 2022). "AQP3-facilitated glycerol transport generates ATP and mediates the growth and survival of tumor cells and, additionally, AQP3 ability to permeate H2O2 may promote tissue inflammation by increasing reactive oxygen species in macrophages and contribute to the setting of inflammatory response." (PMID 35187089, 2022). "Moreover, AQP1 and AQP3 protein expression was highest in poorly differentiated tumors, whereas AQP5 is more expressed in moderately differentiated tumors, suggesting that AQPs are associated with tumor aggressiveness." (PMID 33178018, 2020). "Furthermore, AQP5 and AQP3 were suggested to be involved in proliferation and tumor transformation as a simultaneous overexpression was found to be correlated with an increased expression of EGFR, Ki-67, CK7, and a decrease of E-cadherin and increase of Vimentin." (PMID 33178018, 2020). "For sample P4.2, STModule identifies signal of inflammation (I; AQP3) and spatial expression of ATF3 (II), which plays an important role in regulating immune responses and exhibits dual functions as an oncogene or tumor suppressor." (PMID 40033360, 2025). "Among the AQPs, AQP1, AQP3 and AQP5 have been consistently identified as being aberrantly expressed in various tumor types." (PMID 39941100, 2025). "Compared to conventional biomarkers such as CA19-9, which lacks specificity and sensitivity, AQP3 and AQP5 provide a mechanistic link to tumor biology by modulating key oncogenic pathways." (PMID 40305202, 2025). "Compared to existing biomarkers, such as CA19-9, which lacks specificity and sensitivity, AQP3 and AQP5 offer a mechanistic link to tumor biology, providing insights into disease progression and patient clinical outcomes." (PMID 40305202, 2025). "The IHC signals for NDUFA4L2 and ANKRD45 were stronger in tumor tissue treated with CUMS, while AQP3 expression was weaker compared to the control, and the mRNA levels of signature genes are consistent with the IHC results." (PMID 39409106, 2024). "However, the downstream mechanism of AQP3-mediated tumor suppression is relatively unknown." (PMID 39060229, 2024). "Data shows that AQP3 expression is upregulated in HCC and that high expression of AQP3 is significantly positively correlated with tumor grade, tumor stage, and lymph node metastasis in HCC patients." (PMID 39048663, 2024). "In addition to AQP1, AQP3 may also play a role in tumor angiogenesis." (PMID 39440058, 2024). "AQP3 is upregulated, while AQP7 and AQP9 are downregulated in HCC, with AQP3 expression correlating with aggressive tumor features." (PMID 39596202, 2024). "In the context of NSCLC, the overexpression of AQP1, AQP3, AQP4, and AQP5 has been demonstrated to facilitate tumor angiogenesis, as well as the proliferation, migration, and invasiveness of tumor cells." (PMID 39440058, 2024).
tumor (continued). "The AQP1 expression, AQP3 expression and AQP5 expression were related to regional lymph node metastasis, histological grading, and tumor location of CRC, respectively." (PMID 37334171, 2023). "The relevance of AQP3 and AQP5 in cell migration and their implication in tumor progression was investigated in cells silenced for each paralog separately and simultaneously." (PMID 35455986, 2022). "AQP3 and/or AQP5 silencing was related with weak cell–cell adhesion, suggesting an involvement of AQPs in tumor metastases." (PMID 35455986, 2022). "AQP3 overexpression in TNBC was prognostic of poor five-year disease-free survival and overall survival as well as tumor size, lymph node status, and metastasis." (PMID 36212456, 2022). "On the other hand, in domain 4, we observed upregulation of KRT8, AQP3, KLHDC7B and CDH1, which tend to exhibit stronger tumor progression and metastasis, and high expression of genes NUPR1 and DBI associated with chemotherapy resistance." (PMID 36250636, 2022). "When circHIPK3 was silenced, both AQP3 mRNA and protein levels were reduced and miR-124 was upregulated, resulting in reduced HCC cells proliferation in vitro and suppressed tumor growth in vivo." (PMID 35187089, 2022). "The fact that AQP3 facilitates the transport of both, water and glycerol, together with H2O2 puts AQP3 high on the list of potential targets for tumour therapy." (PMID 33947079, 2021). "circHIPK3 has been reported to be a tumor-related molecule in HCC, and functions as a sponge for miR-124 to control AQP3 expression." (PMID 33858418, 2021). "When AQP3 is knocked down, transport of extracellular H2O2 into cells decreased, consequently leading to diminished tumor growth." (PMID 30555637, 2018). "Both AQP3 positive staining and AQP5 positive staining were localized in the cytoplasm and membrane of tumor cells in HCC tissues." (PMID 24224160, 2013). "Overall, these results indicated that AQP3 and AQP5 are involved in the development of several tumor types, especially in HCC, but the two proteins function as tumor promoter or tumor suppressor in different tumor types." (PMID 24224160, 2013). "Although the role of AQP3 and AQP5 in human tumor pathology has been explored extensively, their molecular mechanisms in different tumor types have not been fully elucidated." (PMID 24224160, 2013). "The modulation of these genes’ expression was analyzed, according to the age range and gender of the patients and the grade of tumor invasiveness and aggressiveness, and was further correlated with the gene expression of AQP1, AQP3, AQP5, and AQP9, previously reported." (PMID 40305202, 2025). "Thus, AQP3 and AQP5 are involved in tumor progression in HCC patients and are closely related to the prognosis of these patients." (PMID 39048663, 2024). "Knock-down of AQP3 in HeLa cell line attenuated the entry of NOX4-derived H2O2 into the cells induced by TGF-β1 and the migration and invasive capacity of HeLa cells, and which was confirmed by the nude mouse xenograft tumor model." (PMID 38230207, 2024). "In addition, the coexpression of the AQP3 and AQP5 proteins is positively correlated with elevated serum AFP levels, tumor stage, and tumor grade." (PMID 39048663, 2024). "Therefore, the elevation of AQP3 and AQP5 expression proves advantageous in augmenting the aggressiveness of tumor cells." (PMID 39440058, 2024). "Additionally, when AQP3 is inhibited, the transfer of extracellular H2O2 into cells is reduced, resulting in decreased tumour development." (PMID 38336645, 2024). "Importantly, elevated AQP3 expression showed a statistically significant influence on PFS and borderline significance on OS, suggesting a possible role in tumor growth and poor prognosis." (PMID 39060229, 2024). "Importantly, mechanistic investigations indicated that AQP3 promoted M2 macrophage polarization by the PPAR-γ/NF-κB axis, which affected tumor growth and migration via modulating IL-6 production." (PMID 39060229, 2024).
tumor (continued). "Our analysis revealed a negative correlation between tumoral AQP3 expression and patients' survival rate by using the Tumor Immune Estimation Resource (TIMER) database." (PMID 38463942, 2024). "The aquaporin 3 (AQP3) gene in NSCLC cells mediates the adhesion of floating cells by the action of protrusions on the cell surface, hence increasing the aggregation of tumor cell invasion." (PMID 36793588, 2023). "It is worth noting that AQP3 expression was not influenced either by gender or tumor characteristics." (PMID 36233821, 2022). "We further constructed gene modules in AT2 (LUAD) and basal (LUSC) cells, which revealed that many tumor-related genes in cells from stage-I patients, including PIGR, AZGP1, BTG2, EGR1, and LMO3 in AT2 cells from LUAD, and AQP3, SPHK1, PPT1, and PDIA6 were found in basal cells from LUSC." (PMID 35027529, 2022). "AQP3, a member of the AQP5 homoprotein family, has been proven to promote tumor development by activating autophagy, which prompted us to hypothesize that AQP5 might regulate autophagy to determine the fates of GC-CSCs." (PMID 36372898, 2022). "Moreover, expression of AQP1, AQP3, and AQP5 was found among tumor-infiltrating lymphocytes surrounding bronchogenic carcinoma cells." (PMID 35847914, 2022). "Although, RNAseq studies do not provide the relative expression of V1aR, V2R, and AQP3 in matching normal and tumor tissues from the same patient." (PMID 35874817, 2022). "In the subgroup analysis of different tumor stages, we found that only stage I LUAD patients showed a shorter OS in the high–AQP3 expression group, which suggested that AQP3 may exert a significant role in an early stage of LUAD." (PMID 34708074, 2021). "For instance, the expression of AQP3 was reported to be upregulated in NSCLC and knockdown of its expression could suppress tumor growth and prolong survival of patients." (PMID 34708074, 2021). "The role of AQP3 in angiogenesis and invasion was suggested to involve regulation of the expression of epithelial-mesenchymal transition (EMT) molecules and reorganization of actin cytoskeleton, controlling tumor cell migration and invasion." (PMID 31379986, 2019). "The AQP3 expression was significantly higher in HCC tissues with advanced TNM stage as compared with those with early TNM stage (P = 0.040), and the tissues with AQP3 overexpression exhibited marked tumor metastasis (p = 0.019)." (PMID 31197130, 2019). "In conclusion, our data suggest for the first time that the aberrant expression of AQP3 and AQP5 proteins may be strongly related to tumor progression and prognosis in patients with HCC." (PMID 24224160, 2013). "Recent studies have showed the altered expression of AQP3 and AQP5 in various tumor types." (PMID 24224160, 2013). "1-, 2- and 4-year recurrence-free survival (RFS) was 90%, 79% and 22% in patients exhibting AQP3-negative tumours compared to 80%, 77% and 60% in patients with AQP3-positive tumours." (PMID 23043286, 2012). "Multivariate Cox regression analyses for RFS, PFS and CSS revealed statistically significant differences between AQP3 positive and negative tumours in relation to PFS." (PMID 23043286, 2012). "59% of patients were shown to exhibit AQP3-positive tumours, whereas 41% of tumours did not express the marker." (PMID 23043286, 2012). "59% of patients were shown to exhibit AQP3-positive tumours, whereas 41% of patients and tumours, respectively, did not express the marker." (PMID 23043286, 2012). "A detailed analysis of the various expression patterns of AQP3 in tumours by scoring both the labeling intensity and the proportion of positively-labeled tumour areas were not performed due to the low number of AQP3-positive tumours (n=51)." (PMID 23043286, 2012). "However, PPAR-γ agonists did not affect tumorigenesis in the Aqp3 knockout mice, but IL-6 secretion increased the number of nodules and tumor proliferation." (PMID 39060229, 2024).
tumor (continued). "We still do not understand the link between H2O2 transport through aquaporins and the tumor malignancy, nor with the therapy resistance, but a study on colon cancer cells correlated the higher expression of AQP3 and AQP5 with the resistance to H2O2-induced stress." (PMID 37175840, 2023). "Interestingly, irrespective of CAP treatment, tumor organoids were expressing 2-fold less Aqp1, Aqp4, and 10-fold less Aqp3 levels than normal organoids, whereas Aqp5 expression was increased." (PMID 35169122, 2022). "By contrast, tumour recurrence was independent of AQP3 expression." (PMID 23043286, 2012). "Furthermore, the absence of AQP3 impedes tumor promoter-induced cell proliferation." (PMID 39440058, 2024). "Interestingly, AQP3 expression was present regardless of gender and tumor characteristics." (PMID 36233821, 2022). "In contrast to tumor cell lines, nontumorigenic breast epithelial cell line, MCF10A, did not change activity of the pathway regardless of the treatment or AQP3 silencing." (PMID 37175840, 2023). "Furthermore, the relationship between AQP3 and AQP5 and tumor invasiveness should not be overlooked." (PMID 39440058, 2024). "The exact mechanism by which AQP3 achieves its effect on tumor resistance is not clear, but it could be through regulation of ROS levels, as SW620 and HCT 116 had a lower relative expression of AQP3 than the two resistant cell lines." (PMID 34829727, 2021). "According to the GEPIA database, AQP1, AQP3, AQP4, and AQP9 were significantly expressed in LUAD tissues compared to normal lung tissues (p < 0.05), but some genes including AQP0, AQP5, AQP6, AQP7, AQP8, AQP10, and AQP11 were not differentially expressed between tumor and normal tissues." (PMID 34708074, 2021).